PTCSC3 (papillary thyroid carcinoma susceptibility candidate 3)
Gene: Long non-coding RNA gene on chromosome 14 (36,130,677 to 36,217,284, reverse strand). Ensembl gene ENSG00000259104.
Diseases named in the same sentence as PTCSC3 in open-access papers:
PTCSC3 is named in the same sentence as 32 diseases in open-access papers, as found by Europe PMC text mining. Sharing a sentence is not in itself a finding about the gene and the disease. The quoted sentences say what the papers report.
thyroid cancer (36 papers, 2013 to 2026). "Candidate papillary thyroid carcinoma susceptibility gene 3 (PTCSC3) is a suppressor of thyroid cancer and glioma." (PMID 39063437, 2024). "LincRNA Papillary Thyroid Carcinoma Susceptibility Candidate 3 (PTCSC3) is considered as a tumor-suppressor in thyroid cancer and glioma." (PMID 37888204, 2023). "In this study, we showed that lncRNA papillary thyroid cancer susceptibility candidate 3 (PTCSC3) was significantly downregulated in papillary thyroid carcinoma (PTC)." (PMID 34337858, 2021). "The expression of PTCSC3 (Papillary thyroid carcinoma susceptibility candidate 3) is strictly thyroid-specific and is downregulated in thyroid cancer." (PMID 32760219, 2020). "Another lncRNA known as papillary thyroid carcinoma susceptibility candidate 3 (PTCSC3) associated with ATC progression and doxorubicin resistance by targeting signal transducer and activator of transcription 3 (STAT3) protein." (PMID 33126409, 2020). "Thyroid carcinoma susceptibility candidate 3 (PTCSC3) down-regulation was observed in the clinical samples as well the cell lines resulting in elevation of miR-574-5p and subsequently down-regulation of SCAI and activation of β-catenin." (PMID 33158279, 2020). "In thyroid carcinoma, several papillary thyroid carcinoma susceptibility candidates, such as PTCSC2, contain a risk-variant rs965513, and PTCSC3 encompasses rs944289; two lincRNA expression levels are strongly down-regulated in thyroid carcinoma tissues." (PMID 32523949, 2020). "In our noncoding DEGs, the PTCSC3 (papillary thyroid carcinoma susceptibility candidate 3) gene was reported to be associated with thyroid cancer." (PMID 31118907, 2019). "lncRNA HULC (highly upregulated in liver cancer) and lncRNA PTCSC3 (papillary thyroid carcinoma susceptibility candidate 3) are two classic cases in this field, highlighting different roles of miRNA–lncRNA competitive interactions." (PMID 29340250, 2018). "LncRNA PTCSC3 initially demonstrated that it was a susceptible gene in papillary thyroid carcinoma and that is also maintains the role of inhibition in thyroid cancer invasion." (PMID 28187755, 2017). "In thyroid cancer, one such example of oncogenic lncRNA is papillary thyroid carcinoma susceptibility candidate 3 (PTCSC3)." (PMID 25289082, 2014). "The present study provides information concerning the function of PTCSC3; however, further investigations are required on lncRNA PTCSC3 and its association with miRNAs in thyroid cancer." (PMID 23599737, 2013). "Papillary thyroid carcinoma susceptibility candidate 3 (PTCSC3) is a newly identified non-coding RNA, which is highly thyroid-specific." (PMID 23599737, 2013). "Additionally, PTCSC3 is located near the SNP rs944289 (3.2 kb downstream of rs944289), which this SNP suppresses PTCSC3 expression by destroying a transcription factor-binding site in the promoter and increases the susceptibility to thyroid cancer." (PMID 37644548, 2023). "For instance, association analysis of the known risk loci certified through the genotyping of cancer patients elucidated the existence of a certain relationship between ANRIL, glioma, and basal cell carcinoma as well as an association of PTCSC3 with thyroid cancer." (PMID 33422052, 2021). "Generally, the risk allele may involve in the reduction of PTCSC2 and PTCSC3 expression and the increased risk of thyroid cancer." (PMID 29416703, 2018). "Recently, a class of long intergenic noncoding RNAs named papillary thyroid cancer susceptibility candidate (PTCSC), such as PTCSC1 (located in 8q24), PTCSC2 (located in 9q22) and PTCSC3 (located in 14q13), might predispose infected persons to thyroid cancer." (PMID 29416703, 2018). "Although the understanding of this lncRNA is far from complete, the evidence gathered thus far depicts PTCSC3 as a fundamental ceRNA and epigenetic regulator that successfully restrains thyroid carcinoma from progressing into a more aggressive form." (PMID 41489907, 2026).
thyroid cancer (continued). "However, rs7958904 may alter HOTAIR’s secondary structure (in silico CRC-related study), H19 rs2839698 is linked to higher risk in digestive system cancers, and PTCSC3 rs944289 reduces promoter activity and PTCSC3 expression in thyroid carcinoma (GWAS Catalog: GCST000335)." (PMID 41463069, 2025). "For instance, PTCSC3 located on chromosome 14q.13.3 was first discovered to be abnormally low in thyroid cancer." (PMID 38997703, 2024). "PTCSC3 was first identified to be downregulated in thyroid cancer, where it acts as a tumor suppressor lncRNA." (PMID 37644548, 2023). "Several lncRNAs, such as MALAT1, BANCR, and PTCSC3, have been identified to promote the proliferation and metastasis of thyroid cancers." (PMID 38298184, 2023). "In thyroid carcinoma, some lncRNA are discussed in the gene regulation of disease progression, such as PTCSC3, with XLOC 051122 and XLOC 006074 in local metastasis and PANDAR as a possible target in pro-apoptotic therapies for carcinoma." (PMID 35594253, 2022). "To investigate the role of PTCSC3 in thyroid cancer, we analysed the expression of PTCSC3 in 68 pairs of frozen PTC samples and their adjacent normal tissues by using qRT‐PCR." (PMID 34337858, 2021). "Taken together, these data demonstrated that PTCSC3 upregulation suppresses thyroid cancer growth both in vitro and vivo." (PMID 34337858, 2021). "A cancer-associated SNP located with the lncRNA PTCSC3 reduces the binding affinity of the transcription factor C/EBPα, resulting in decreased PTCSC3 promoter activation and reduced expression of the lncRNA which is evident in thyroid carcinoma." (PMID 33499210, 2021). "They found that the levels of VEGF and MMP-9 in BCPAP thyroid cancer cells expressing PTCSC3 were significantly downregulated to inhibit invasion and metastasis." (PMID 32596158, 2020). "rs944289 located on chromosome 14q13.3 regulates expression of the PTCSC3 lncRNA, which has tumor suppressor effect in thyroid cancer cell lines, through the recruitments of C/EBPα and β transcription factors." (PMID 33551988, 2020). "It is known that lncRNA PTCSC3 inhibits thyroid cancer and glioma and STAT3 promotes cancer development." (PMID 31171714, 2019). "We proved that PTCSC3 as a formerly characterized tumor suppressor in thyroid cancer and glioma was likely an upstream inhibitor of HOTAIR, and the inhibition of HOTAIR by PTCSC3 is involved in the regulation of LSCC cell proliferation." (PMID 31171714, 2019). "PTCSC3 is a tumor suppressor in both thyroid carcinoma and glioma, and overexpression of PTCSC3 inhibits tumor progression by inhibiting cancer cell proliferation." (PMID 31196168, 2019). "Both PTCSC2 and PTCSC3 can play an important anti-tumor role by affecting the expression levels of other genes in thyroid cancer, but the specific mechanisms require further investigation." (PMID 29416703, 2018). "Overexpression of PTCSC3 can reduce the expression of miR-574-5p by acting as a ceRNA for miR-574-5p in different thyroid cancer types (of papillary, follicular and anaplastic origin)." (PMID 29416703, 2018). "Compared with lncRNA HULC, lncRNA PTCSC3 is a newly identified noncoding RNA that is dramatically downregulated in thyroid cancers and has been studied as a tumor suppressor that competes with endogenous RNA for miR-574-5p." (PMID 29340250, 2018). "Subsequently, lncRNA PTCSC3 was reported to be a tumor suppressor in thyroid cancer, and the mechanism study demonstrated that lncRNA PTCSC3 reduced cell motility and invasiveness by downregulating the S100A4 pathway." (PMID 28187755, 2017). "The analysis of tumor cell proliferation and invasion abilities in lncRNA PTCSC3-elevated cells showed the inhibitory role of lncRNA PTCSC3 in glioma, which is similar to its role in thyroid cancer." (PMID 28187755, 2017). "Transfection of PTCSC3 into thyroid cancer cells results in significant growth inhibition, cell cycle arrest, and increased apoptosis." (PMID 26872371, 2016).
thyroid cancer (continued). "PTCSC3 is dramatically decreased in thyroid cancers and has the characteristics of a tumor suppressor." (PMID 26872371, 2016). "The transfection of PTCSC3 resulted in significant growth inhibition in all tested thyroid cancer cell lines (BCPAP, FTC133, and 8505C)." (PMID 24672386, 2014). "Out of 20 miRNAs, miR-574-5p was selected to further confirm the inverse correlation of over-expression of PTCSC3 with growth of thyroid cancer cells in vitro." (PMID 24672386, 2014). "In the present study, the effect of PTCSC3 on cell growth and apoptosis in thyroid cancer cells was evaluated and the possible binding of PTCSC3 with specific miRNAs was studied by bioinformatic and biological analyses." (PMID 23599737, 2013). "The highly thyroid-specific expression of PTCSC3 and downregulated expression in PTC tissues and cell lines implicated its potential role in thyroid cancer." (PMID 23599737, 2013). "In order to assess the inhibitory effect of PTCSC3 on thyroid cancer cells, a cell growth assay was performed." (PMID 23599737, 2013). "Following transfection with PTCSC3, all three thyroid cancer cells originating from various pathological types of thyroid cancers demonstrated significant growth inhibition, cell cycle arrest and increased apoptosis." (PMID 23599737, 2013). "The present study aimed to investigate the effects of PTCSC3 on the biological features of thyroid cancer cells and to explore its possible function as a competing endogenous RNA to bind with miRNAs." (PMID 23599737, 2013). "The significant inverse correlation between PTCSC3 and miR-574-5p suggests that PTCSC3 acts as a competing endogenous RNA to target miRNAs and in turn regulate cell growth and apoptosis in thyroid cancer." (PMID 23599737, 2013). "In this study, PTCSC3, as a target of miRNAs involved in thyroid cancer, was investigated using in silico and biological analyses." (PMID 23599737, 2013). "The top 20 miRNAs to have a potential interaction with PTCSC3 were identified, out of which miR-574-5p was selected to further confirm the inverse correlation with PTCSC3 in thyroid cancer cells in vitro." (PMID 23599737, 2013). "For instance, PCAT1, PVT1, and PCAT19 in prostate cancer, CUPID1 and CUPID2 in breast cancer, PTCSC2 and PTCSC3 in thyroid cancer, LINC00673 in pancreatic cancer, lncPSCA in gastric cancer, as well as LCETRL3 and LCETRL4 in non-small cell lung cancer, are implicated in malignant development." (PMID 37072811, 2023). "As tumour cells usually reprogramme their metabolism for rapid proliferation, in view of the role of PTCSC3 in the proliferation of thyroid cancer, we speculated that PTCSC3 was involved in the aerobic glycolysis regulation of PTC cells." (PMID 34337858, 2021). "Moreover, we further discovered that PTCSC3 inhibited thyroid cancer development by suppressing glycolysis." (PMID 34337858, 2021). "Besides, PTCSC3 suppressed the growth in vivo, indicating that PTCSC3 acts as a tumor suppressor in thyroid cancer." (PMID 33158279, 2020). "PTCSC3 was first identified in thyroid and plays tumour suppressive role in thyroid cancer." (PMID 33126409, 2020). "LncRNA PTCSC3 has been characterized as a tumor suppressor lncRNA in thyroid cancer and glioma." (PMID 31171714, 2019). "Moreover, PTCSC3 inhibits cell growth, promotes apoptosis and arrests cell cycle at G1/S and G2/M phases in thyroid cancer." (PMID 29416703, 2018). "Papillary thyroid carcinoma susceptibility candidate 3 (PTCSC3) is a newly identified and highly thyroid-specific non-coding RNA." (PMID 26872371, 2016). "Collectively, our data demonstrate that overexpression of PTCSC3 in thyroid cancer cells inhibits cellular proliferation and induces cell cycle arrest and apoptosis, suggesting that dysfunction of PTCSC3 in thyroid cancer may be a common molecular event." (PMID 23599737, 2013).
thyroid cancer (continued). "Moreover, understanding the molecular mechanisms of PTCSC3 in thyroid cancer is fundamentally important in developing new molecular markers for earlier diagnosis and novel therapeutic targets." (PMID 23599737, 2013). "As the majority of lncRNAs share the same biogenesis mechanisms and have a similar structure with mRNAs, including the 5-UTR, ORF and 3-UTR, it is logical to assume that PTCSC3, a lncRNA, may be targeted by certain miRNAs that are upregulated in thyroid cancers." (PMID 23599737, 2013). "However, as an lncRNA, the presence and significance of PTCSC3 in thyroid cancer is undetermined." (PMID 23599737, 2013). "Sedaghati summarized the dysregulated and functional LncRNAs in thyroid cancer, including 28 upregulated LncRNAs, such as ANRIL, BANCR, H19, HOTAIR, MALAT1, and NEAT1, and 22 downregulated LncRNAs, including GAS5, NAMA, PTCSC2, and PTCSC3." (PMID 37874339, 2024). "Furthermore, when treating PTCSC3 overexpressed TPC‐1 and BCPAP cells with the proteasome inhibitor MG132, the protein levels of endogenous PGK1 increased more than those in control cells, suggesting that PTCSC3 promotes the proteasome‐dependent degradation of PGK1 in thyroid cancer cells." (PMID 34337858, 2021).
papillary thyroid carcinoma (15 papers, 2013 to 2023). "Our previous genome-wide association study found two important genes being related to extracranial CAS, papillary thyroid carcinoma susceptibility candidate 3 (PTCSC3) and HDAC9." (PMID 36230983, 2022). "Papillary thyroid carcinoma susceptibility candidate 3 (PTCSC3) is an intergenic long noncoding RNA gene (lincRNA) located at 14q.13.3, which was newly identified as thyroid specific." (PMID 28187755, 2017). "Long noncoding RNA papillary thyroid carcinoma susceptibility candidate 3 (PTCSC3) is a novel lncRNA that was primarily detected in papillary thyroid carcinoma." (PMID 28187755, 2017). "Very interestingly, a study reported that lncRNA PTCSC3 (Papillary Thyroid Carcinoma Susceptibility Candidate 3), located 3.2 kb downstream of SNP rs944289 at 14q.13.3, is strongly downregulated in papillary thyroid carcinoma (PTC)." (PMID 23725405, 2013). "This SNP rs944289 was also found to predispose to PTC through a long intergenic noncoding RNA gene (lincRNA) named papillary thyroid carcinoma susceptibility candidate 3 (PTCSC3) located 3.2 kb downstream of rs944289 at 14q13.3 that has the characteristics of a tumor suppressor." (PMID 35295987, 2022). "Furthermore, according to Jendrzejewski, the SNP rs944289 can predispose to papillary thyroid carcinoma through deregulation of PTCSC3 expression, which acts as a tumor suppressor." (PMID 29178884, 2017). "Experimental data suggest that PTCSC3 has antitumor properties, as its overexpression inhibits thyroid papillary carcinoma cell proliferation and development in vitro and in vivo by suppressing glycolysis and promoting PGK1 ubiquitin-mediated degradation." (PMID 37968670, 2023). "In this study, we observed that PTCSC3 is significantly downregulated in papillary thyroid cancer." (PMID 34337858, 2021). "For example, the signaling pathway PTCSC3-miR-574-5p-SCAI-Wnt/catenin mediates the proliferation and migration of PTC-1 cells, which is essential for further treatment and prognosis of papillary thyroid carcinoma." (PMID 34134589, 2021). "One functional lincRNA (MIAT) was first identified during the experimental interrogation of an intergenic TAS, and another lincRNA PTCSC3, was identified nearby a TAS found from a papillary thyroid carcinoma GWAS, perhaps representing the first of many such discoveries to come from intergenic TASs." (PMID 23818866, 2013).
glioma (7 papers, 2017 to 2024). A benign or malignant brain and spinal cord tumor that arises from glial cells (astrocytes, oligodendrocytes, ependymal cells). "As lncRNA PTCSC3 was downregulated in glioma cell lines, the gain-of-function experiment was performed using lentivirus vector in the U87 and U251 glioma cell lines." (PMID 28187755, 2017). "Among the four glioma cell lines, U87 had the lowest expression level of lncRNA PTCSC3 compared with U251, SHG44 and SHG139." (PMID 28187755, 2017). "The expression level of lncRNA PTCSC3 in human microglia and glioma cell lines was examined using quantitative real-time polymerase chain reaction (qRT-PCR)." (PMID 28187755, 2017). "To investigate the biological function of lncRNA PTCSC3, we performed gain-of-function experiments in glioma cell lines." (PMID 28187755, 2017). "The overexpression of lncRNA PTCSC3 inhibits proliferation, migration and invasion of glioma cells and suppresses the Wnt/β-catenin signaling pathway through targeting LRP6." (PMID 28187755, 2017). "The expression level of lncRNA PTCSC3 in glioma was detected in human microglia cells, astrocyte and four glioma cell lines (U87, U251, SHG44 & SHG139) by qRT-PCR." (PMID 28187755, 2017). "LncRNA PTCSC3 inhibits the proliferation and migration of glioma cells and suppresses Wnt/β-catenin signaling pathway by targeting LRP6." (PMID 28187755, 2017). "These experiments indicate that overexpression of lncRNA PTCSC3 inhibited proliferation, migration and invasion in glioma cells." (PMID 28187755, 2017). "Scratch test and transwell assay were used to evaluate the affect of lncRNA PTCSC3 on glioma cell migration and invasion respectively." (PMID 28187755, 2017). "LncRNA PTCSC3 was downregulated in glioma cell lines compared with human microglia cells and astrocyte." (PMID 28187755, 2017). "Our study illuminated a complicated mechanism network of how lncRNA PTCSC3 regulated glioma progression." (PMID 28187755, 2017). "Our study was performed to assess the expression of lncRNA PTCSC3 in glioma cells and to evaluate its role and mechanism in tumor cell proliferation, invasion and migration." (PMID 28187755, 2017). "We demonstrated that lncRNA PTCSC3 was downregulated in glioma cells compared with normal brain cells." (PMID 28187755, 2017). "We assessed the expression level of lncRNA PTCSC3 in human microglia and glioma cell lines." (PMID 28187755, 2017). "LncRNA PTCSC3 was significantly downregulated in glioma cell lines." (PMID 28187755, 2017). "In the present study, we detected the expression level of lncRNA PTCSC3 in glioma." (PMID 28187755, 2017). "In conclusion, lncRNA PTCSC3 is downregulated in glioma cells." (PMID 28187755, 2017). "This is the first time that lncRNA PTCSC3 was reported in glioma." (PMID 28187755, 2017). "This is the first time that lncRNA PTCSC3 has been assessed in glioma." (PMID 28187755, 2017). "U87 and U251 were selected to investigate the biological function of lncRNA PTCSC3 in glioma cells." (PMID 28187755, 2017). "LncRNA PTCSC3 is a potential therapeutic target for treatment of glioma." (PMID 28187755, 2017). "Our results showed that lncRNA PTCSC3 was downregulated in glioma cells." (PMID 28187755, 2017). "LncRNA PTCSC3 is a potential novel therapeutic target for intervention of glioma." (PMID 28187755, 2017). "However, the biological function and molecular mechanism of lncRNA PTCSC3 in glioma are still unknown." (PMID 28187755, 2017). "In addition, many lncRNAs, including PTCSC3, NEAT1, and BLACAT1, have been reported to regulate Wnt/β-catenin signaling pathway to affect glioma cell growth, migration, and invasion." (PMID 34923953, 2022). "Additionally, we demonstrated that lncRNA PTCSC3 overexpression suppressed proliferation, migration and invasion and inhibited the epithelial-mesenchymal transition (EMT) by suppressing the Wnt/β-catenin signaling pathway in glioma." (PMID 28187755, 2017).